LGR5 (leucine rich repeat containing G protein-coupled receptor 5)
Diseases named in the same sentence as LGR5 in open-access papers (continued):
Sharing a sentence is not in itself a finding about the gene and the disease.
liver fibrosis (5 papers, 2017 to 2024). "This process may explain the underlying mechanism through which GDF11‐induced LGR5+ cells decrease liver fibrosis." (PMID 38494851, 2024). "A similar effect was reported for GDF11, e.g., GDF11 is upregulated in human fibrotic liver and ameliorated liver fibrosis in CCl4-treated mice by promoting LGR5 + LPC expansion." (PMID 37798809, 2023). "Factors like HGF and/or Rspo1 have been shown to promote expansion of these LGR5 + cells and attenuate liver fibrosis in mice." (PMID 37798809, 2023). "More importantly, Lgr5+ liver stem cell transplantation relieved CCL4-induced liver fibrosis, and when Lgr5 was knocked down, the mice developed more severe fibrosis." (PMID 29079780, 2017). "We observe Lgr5+ liver stem cells in human liver fibrosis tissues, and once they are isolated, these cells are able to form organoids, and treatment with HGF/Rspo1 promotes their expansion." (PMID 29079780, 2017). "Lgr5+ cells sorted from the liver fibrosis model formed organoids, which were similar in number and size to those formed by cells sorted from the 1XCCL4 damage model." (PMID 29079780, 2017). "Using an antibody against Lgr5 for immunostaining, we observed that Lgr5 was essentially undetectable in the normal liver, whereas clear Lgr5-positive cells were observed in liver fibrosis samples." (PMID 29079780, 2017). "Single Lgr5+ human liver cells were isolated from these fresh liver fibrosis samples by FACS sorting using a FITC-labeled anti-Lgr5 antibody." (PMID 29079780, 2017). "Lgr5+ cells from different conditions (1XCCL4 treatment alone or liver fibrosis model plus rHGF and rRspo1 treatment) demonstrated similar abilities to form the organoids, which were in a similar shape, number, and size." (PMID 29079780, 2017). "According to our current data, Lgr5+ liver stem cells induction not only inhibited the development of liver fibrosis but also attenuated the established fibrosis." (PMID 29079780, 2017). "In mouse models of hepatic fibrosis, LGR5+ LPCs treated with GDF11 suppressed fibrogenesis." (PMID 38494851, 2024). "Likewise, another study showed that carbon tetrachloride treatment promotes Lgr5+ liver stem cell proliferation and improves liver fibrosis, whereas Lgr5 knockdown worsens fibrosis." (PMID 36168631, 2022). "We next investigated whether endogenous Lgr5+ liver stem cells played a crucial role in the development of liver fibrosis." (PMID 29079780, 2017). "In addition, Lgr5+ liver stem cells are also observed in patients diagnosed with liver fibrosis, and rHGF/rRspo1 proteins can increase the number of human Lgr5+ liver stem cells in vitro." (PMID 29079780, 2017). "Together, our results suggest that Lgr5+ liver stem cells may work to alleviate Lgr5 expression-dependent liver fibrosis." (PMID 29079780, 2017). "Together, these results indicate that Lgr5+ liver stem cells exist in human liver fibrosis tissues, and that the therapeutic approach for liver fibrosis using rHGF combined with rRspo1 injection to induce more Lgr5+ liver stem cells may also work in humans." (PMID 29079780, 2017). "Next, we infected the mice with Ad-Lgr5 shRNA to disable endogenous Lgr5+ liver stem cells to investigate whether Lgr5+ liver stem cells played a crucial role in liver fibrosis development." (PMID 29079780, 2017). "Moreover, when the Lgr5+ cells sorted from the liver fibrosis model were cultured in a differentiation medium (DM), they expressed mature hepatic genes, and abundant amounts of albumin and AAT were secreted into the medium." (PMID 29079780, 2017). "However, the mechanism of how Lgr5+ liver stem cells inhibit liver fibrosis formation is still unclear." (PMID 29079780, 2017). "In addition, our unpublished data demonstrated that isolated human Lgr5+ liver stem cells from liver fibrosis samples can be cultured and differentiated into functional mature hepatocytes in vitro." (PMID 29079780, 2017).
liver fibrosis (continued). "Next, we detected whether Lgr5+ liver stem cells were maintained upon chronic damage during CCL4-induced liver fibrosis development." (PMID 29079780, 2017). "Lgr5 expression peaked at day 5 and maintained this level during the development of liver fibrosis." (PMID 29079780, 2017). "Moreover, Lgr5+ liver stem cells were isolated from human liver fibrosis tissues, and single human Lgr5+ liver cells expanded as organoids, which could be further enhanced by treatment with HGF and Rspo1 proteins in vitro." (PMID 29079780, 2017). "Furthermore, our ongoing studies have demonstrated that Lgr5+ liver stem cells conditional medium can reverse activated HSCs to quiescent HSCs, which indicates that Lgr5+ liver stem cells may reduce liver fibrosis through the direct secretion of specific factors." (PMID 29079780, 2017). "To verify whether rHGF/rRspo1 recovers the liver functions through Lgr5+ liver stem cells induction, we knocked down Lgr5 expression using Ad-Lgr5 shRNA infection in the CCL4-induced liver fibrosis model." (PMID 29079780, 2017). "Using FACS, we isolated Lgr5-GFP+ liver stem cells from Lgr5-GFP mice treated with 1XCCL4, and injected these cells intrasplenically into the wild-type C57 mice with acute liver damage (single CCL4 treatment) or chronic liver damage (liver fibrosis model, 2XCCL4 treatment/week for 6 weeks)." (PMID 29079780, 2017). "To further investigate whether Lgr5+ liver stem cells exist in the injured human liver, we obtained samples from 42 patients with clinically diagnosed liver fibrosis, and 5 normal liver samples from automobile accident victims without liver fibrosis to be used as control." (PMID 29079780, 2017).
lung carcinoma (5 papers, 2016 to 2023). "Previously, we showed that LGR4 was highly expressed in the lung cancer cell line A549 and RNA-seq expression data showed no expression of LGR5, LGR6, RNF43, and ZNRF3 in A549 cells." (PMID 37402772, 2023).
skin cancer (5 papers, 2011 to 2022). "To further examine the contribution of Lgr5+ HFSCs with Pten loss and their progeny to skin tumor development, we used Lgr5-CreER; Ptenflox/flox; Rosa-mTmG (Lgr5-Pten-/--mTmG) and Lgr5-CreER;Rosa-mTmG (Lgr5-mTmG) mice (control)." (PMID 31754399, 2019). "Moreover, progeny of Lgr5+ HFSCs contribute to papillomavirus-induced SCC, the second most common skin cancer." (PMID 31754399, 2019).
small intestinal tumors (5 papers, 2014 to 2022). "The mice had developed small intestinal tumors most likely caused by 4-OHT ingestion activating the mutant allele in Lgr5-expressing cells of the gastrointestinal (GI) tract (data not shown)." (PMID 26771241, 2016). "Consistently, in organoids derived from small intestine tumours in ApcMin/+ mice treated with the SETD7 inhibitor (R)-PFI-2 showed reduced initiation of spheres and lower Wnt-dependent gene expression (Lgr5, Axin2 and Lyz1)." (PMID 35326563, 2022).
soft tissue sarcoma (5 papers, 2011 to 2024). A malignant neoplasm arising from muscle tissue, adipose tissue, blood vessels, fibrous tissue, or other supportive tissues excluding the bones. "In addition, the LGR5 locus was recently identified to be among the most frequently amplified loci in a genome-wide study of soft tissue sarcomas (copy number in top 1% of nearly 19,000 genes) suggesting that up-regulation of LGR5 may contribute to sarcoma pathogenesis." (PMID 23596566, 2013). "In a previous work our group demonstrated the mRNA expression of the LGR5 transcript variant LGR5Δ5, but not the expression of full length LGR5 (LGR5FL) being an independent unfavourable prognostic marker for soft tissue sarcoma patients (STS)." (PMID 30770730, 2019). "However, there has been no investigation regarding the expression and function of LGR5/GPR49 in soft-tissue sarcomas (STS) yet." (PMID 21978106, 2011).
squamous cell carcinoma (5 papers, 2018 to 2024). A carcinoma arising from squamous epithelial cells. "Lgr5 is highly expressed in squamous cell carcinomas in the oral cavity and esophagus and may play a role in cancer stem cell properties." (PMID 39684417, 2024). "However, the role of Lgr5 in squamous cell carcinoma remains a topic of debate." (PMID 39684417, 2024).
acute myeloid leukemia (4 papers, 2012 to 2023). Acute myeloid leukemia (AML) is a group of neoplasms arising from precursor cells committed to the myeloid cell-line differentiation. "The abnormal expression of LGR5 in acute myeloid leukemia cells counteracts the effects of OSR1 overexpression, resulting in reduced cell survival and proliferation." (PMID 37627077, 2023). "The reported tumor stem cell markers also included Aldehyde dehydrogenase (ALDH1), Musashi-1, LgR5, the prostate stem cell antigen (PSCA), Doublecortin and CaM kinase-like-1 (DCAMKL-1), and acute myeloid leukemia (AML) stem cell-surface marker TIM3." (PMID 22634835, 2012).
ankyloglossia (4 papers, 2011 to 2022). A developmental abnormality in which the bottom of the tongue is attached to the floor of the mouth. "Since Lgr5 KOs generated from both transgenic lines show neonatal lethality associated with ankyloglossia, histological analyses were performed at E18.5 (Fig EV1A)." (PMID 32468660, 2020). "LGR gene knockout mice showed neonatal lethality due to a breast-feeding defect caused by ankyloglossia, suggesting an involvement of LGR5 in craniofacial development." (PMID 22163301, 2011). "This malformation, called ankyloglossia, is accompanied by gastrointestinal tract dilatations and corresponds to a higher expression of LGR5 on the labial side of the developing lingual groove." (PMID 36133922, 2022). "Surprisingly, the direct sequencing of the Lgr5 gene in humans with ankyloglossia did not reveal any mutation in this gene." (PMID 36133922, 2022).
colorectal adenocarcinoma (4 papers, 2020 to 2023). The most common type of colorectal carcinoma. "To begin to test this hypothesis, we first determined whether there was an association between TCF7L1 and LGR5 expression in tumor and normal colonic tissue samples available in the colorectal adenocarcinoma (COAD) data set within The Cancer Genome Atlas (TCGA) database." (PMID 36833408, 2023). "First, we compared 54 BRAFV600E-mutant colorectal adenocarcinoma (COAD) to 41 healthy colon samples listed in the TCGA database and then calculated the correlation to the LGR5-independent fetal signature (left GSEAs)." (PMID 32792685, 2020).
esophageal cancer (4 papers, 2011 to 2022). A primary or metastatic malignant neoplasm involving the esophagus. "Quante and colleagues found that mice stimulated by bile acid, which is an important intestinal microbial metabolite, were more likely to accelerate the transformation of Barrett's esophagus into esophageal cancer with the expansion of lgr5+ gastric and cardiac progenitor cells." (PMID 33897888, 2021). "Subsequently, researchers sorted out esophageal cancer stem cells from esophageal cancer cells using the SP cell sorting approach with CD44, SOX2 and Lgr5 as the markers." (PMID 28193907, 2017). "Expression of a putative intestinal stem cell marker LgR5 was analyzed in esophageal cancer specimen (n = 70: 41 EAC with BE, 19 EAC without BE, and n = 10 esophageal squamous-cell carcinomas, ESCC) and in the adenocarcinoma cell line OE-33." (PMID 21345220, 2011).
hearing loss (4 papers, 2018 to 2023). "In order to translate these findings to patients that have had hearing loss for a long time, evaluating long-term survival of LGR5+ SCs after trauma is crucial." (PMID 37692553, 2023). "These LGR5+ SCs can be used as an endogenous source of progenitor cells for regeneration of hair cells (HCs) to treat hearing loss and deafness." (PMID 37692553, 2023). "Here, we evaluated Lgr5 expression in the adult cochlea and long-term survival of LGR5+ SCs following severe hearing loss." (PMID 37692553, 2023). "The fact that we also found surviving LGR5+ progenitors after ototoxic trauma opens an opportunity for this treatment of ototoxically induced hearing loss as well." (PMID 34675775, 2021). "Potentially these LGR5 positive (LGR5+) SCs can be utilized as endogenous stem cells for HC regeneration to treat hearing loss including deafness (severe hearing loss)." (PMID 34675775, 2021). "In addition, we determined the expression levels of HC-specific genes: Myo7A, Slc26a5, and Otof and the progenitor cell-specific genes Lgr5, Lgr4, and Sox2 in the mouse cochlea 7 and 28 days after the induction of severe hearing loss." (PMID 37692553, 2023). "LGR5 regulates cochlear development by enhancing the Wnt/β-catenin signaling pathway, especially LGR5-positive SCs have the potential to transdifferentiate into HCs, suggesting that it may be acted as a therapeutic target for hearing loss." (PMID 36311029, 2022). "Moreover, we demonstrated the mRNA expression of Lgr5 is specifically enhanced 7 but not 28 days after onset of cochlear trauma, possibly giving a therapeutic window to treating hearing loss in the future." (PMID 37692553, 2023).
leukemia (4 papers, 2009 to 2024). A malignant (clonal) hematologic disorder, involving hematopoietic stem cells and characterized by the presence of primitive or atypical myeloid or lymphoid cells in the bone marrow and the blood. "To determine whether LGR5 levels are increased in leukaemia, we quantified LGR5 expression in patient-derived, primary acute lymphoblastic leukaemia (ALL), ALL patient-derived xenograft (PDX) models and pre-B-ALL cell lines." (PMID 39169164, 2024). "The qRT-PCR results revealed significant differential expression patterns of LGR5 and VSIG4 in normal and human leukemia cell lines (HL-60 and MV-4-11)." (PMID 38322112, 2024).
lung adenocarcinoma (4 papers, 2018 to 2021). A carcinoma that arises from the lung and is characterized by the presence of malignant glandular epithelial cells. "More recently, Wnt-responsive cells expressing Lgr5 have been reported to be highly proliferative and aggressive in lung adenocarcinoma, suggesting a function for Lgr5 cells in the lungs." (PMID 32157214, 2020). "In addition, factors previously identified to be specific markers of lung adenocarcinoma were upregulated, including PROM2, CLDN3, and TJP3, as were genes proposed to have potential diagnostic or prognostic value in human cancers, including MMP9, AGR2, SULF1, NHSL1, LGR5, MUC1, and PIK3C2G." (PMID 31434729, 2019).
papillary thyroid cancer (4 papers, 2015 to 2019). "Lgr5 and RSPO2 are also associated with tumor aggressiveness, lymph node metastases, and Wnt/β-catenin activation in human papillary thyroid cancer." (PMID 28404917, 2017). "Our data is the first to report that LGR5 and its ligand, RSPO2, are associated with tumor aggressiveness, lymph node metastases, and Wnt/β-catenin activation in human papillary thyroid cancer." (PMID 26416247, 2015).
Salmonella Infections (4 papers, 2014 to 2025). Infections with bacteria of the genus SALMONELLA. "Our study demonstrated that enteritis-causing Salmonella infection resulted in diminished ISCs activity, as evidenced by the downregulation of Lgr5, PCNA, KRT20, and Villin expression." (PMID 40059168, 2025). "It was shown that Lgr5 and ChgA expressions were markedly decreased in the Salmonella infection group." (PMID 35163196, 2022). "Salmonella infection also significantly decreased the expression of intestinal stem cell marker Lgr5 and Bmi 1, as determined by PCR and western blot." (PMID 25214524, 2014). "Moreover, Salmonella infection significantly decreased the expression of intestinal stem cell markers Lgr5 and Bmi1." (PMID 28588586, 2017). "Moreover, our western blot, PCR, and immunofluorescence data show that stem cell marker Lgr5 was reduced by Salmonella infection (determined using a GFP‐labeled Lgr5 organoid system)." (PMID 25214524, 2014). "Moreover, our western blot, PCR, and immunofluorescence data demonstrated that stem cell markers (Lgr5 and Bmi1) were significantly decreased by Salmonella infection (determined using GFP‐labeled Lgr5 organoids)." (PMID 25214524, 2014). "Moreover, we show that stem cell markers (Lgr5 and Bmi1) were decreased by Salmonella infection." (PMID 25214524, 2014).
ulcerative colitis (4 papers, 2021 to 2025). An inflammatory bowel disease involving the mucosal surface of the large intestine and rectum. "Here, we found that in the dextran sulfate sodium (DSS)-induced ulcerative colitis mice model, colon epithelium and Lgr5+ intestinal stem cells (ISCs) renew quickly during the first 3 days." (PMID 34692671, 2021).
acne (3 papers, 2024). An inflammatory process of the sebaceous glands which is characterized by comedones, nodules, papules and/or pustules on the skin. "Three novel acne associated genes are also involved in the Wnt signaling pathway: ZNRF3 and KREMEN1 from 22q12.1 and LGR5 from 12q21.1." (PMID 36922633, 2024). "We detected significant enrichment of TSPAN8, along with other novel genes (LGR5, ZNRF3, KREMEN1) and several known acne susceptibility genes, for the GO biological processes gene sets “GO negative regulation of response to stimulus” and “GO regulation of response to stress”." (PMID 36922633, 2024).
alopecia (3 papers, 2016 to 2022). Hair loss usually from the scalp. "Protection of LGR5+ HFSCs with topical ruxolitinib was associated with suppression of alopecia and enhancement of wound healing after allo-SCT, while topical corticosteroid was not." (PMID 34512636, 2021). "Recently, we found that LGR5+ HFSCs were significantly reduced in mouse cutaneous GVHD, in association with reduced numbers of hair follicles, alopecia, and delayed wound healing." (PMID 34512636, 2021).
Chronic colitis (3 papers, 2020 to 2026). A chronic inflammatory disease of the large intestine (colon, cecum and rectum). "Similarly, intestinal organoids treated with low doses of pro-inflammatory IL-22 or the chronic colitis-associated cytokine TNF-α, displayed a small but significant increase in the percentage of Lgr5+ CBC cells." (PMID 32948837, 2020).
cutaneous squamous cell carcinoma (3 papers, 2018 to 2022). "In contrast, cutaneous squamous cell carcinomas (cSCC) appeared to have preferentially arisen from the infection of Lgr5+ epithelial progenitor cells because they had higher percentages of tdTomato+ cells." (PMID 36016373, 2022). "miR-22 knockout mice showed attenuated Wnt/β-catenin activity and Lgr5+ CSCs penetrance, resulting in reduced occurrence, progression, and metastasis of chemically induced cutaneous squamous cell carcinoma (cSCC)." (PMID 34345013, 2021).
deafness (3 papers, 2021 to 2023). An inherited or acquired condition characterized by the complete loss of the ability to hear from one or both ears. "Because Cx26f/f; Lgr5-CreER mice model has less OHC loss and does not show deafness in the early stage, this model is more conducive to detecting subtle differences between different drugs." (PMID 35688810, 2022).